MYC (MYC proto-oncogene, bHLH transcription factor)
Diseases named in the same sentence as MYC in open-access papers (continued):
Sharing a sentence is not in itself a finding about the gene and the disease.
cancer (continued). "A more detailed understanding of the regulation of MYC expression in cancer cells opens up new targets for drug discovery and new approaches in the treatment of cancer." (PMID 34440124, 2021). "In MYC-driven cancers, MYC regulates the expression of Pontin and Reptin, which interact with β-catenin and MYC." (PMID 33599797, 2021). "High MYC expression in cancer cells promotes microRNA-105 secretion, which in turn acts on CAFs to stimulate MYC activation, thus extending the effects of MYC originating from cancer cells." (PMID 34503536, 2021). "Expression of DKC1 is controlled by c-MYC transcriptionally in MYC-dependent cancers and enhances cell proliferation and growth." (PMID 33599797, 2021). "It exerts simultaneous disruption of two key MYC-mediating factors that promote cancer cell growth (NCT03059147)." (PMID 33840388, 2021). "The KJ-PYR-9 effects on inhibiting proliferation in xenografts bearing MYC-amplified human cancer cells seem promising." (PMID 34372899, 2021). "In pancreatic cancer, CDK7 activity is particularly important for cancer cells in which MYC is upregulated, possibly due to the general increase in transcription driven by this oncogenic transcription factor." (PMID 34092037, 2021). "GSEA analysis revealed that a series of classical hallmarks participated in cancer initialization (such as proto-oncogene MYC hallmarks) and cancer cell cycle acceleration (such as G2M checkpoint hallmark and cell cycle transcription factor E2F hallmark)." (PMID 34421357, 2021). "Accordingly, BRD4 inhibition impairs CDK9 recruitment to MYC, reduces MYC transcripts levels, down-regulates Myc-dependent target genes, and has anti-proliferative effects in cancer cells." (PMID 34146121, 2021). "Unbiased comparison to Hallmark gene sets in GSEA showed strongest enrichment of genes involved in G2/M progression and for target genes of E2F and MYC which are well-known for their role in cell cycling and cancer." (PMID 34584219, 2021). "Cutting edge drug discovery approaches, such as NMR-based fragment screening, also represent attractive strategies for the exploitation of WDR5, and, by extension, MYC, for cancer therapy." (PMID 34299488, 2021). "Particularly for cancer drivers such as MYC, indirect targeting—that is, modulation of genes which are critical for that driver’s effect on cellular signaling but which also can be targeted with small molecules—have yielded several promising results." (PMID 33328249, 2021). "The Shh pathway stimulates CSC self-renewal of a variety of cancers by inducing the expression of several stemness-related genes, including c-MYC, BMI1, Nanog, SOX2, and OCT4." (PMID 33499351, 2021). "This action led to the suppression of MYC-dependent cancer cell proliferation and tumorigenicity both in vitro and in vivo." (PMID 33801599, 2021). "Genetic alterations of c-MYC expression have been found in approximately 70,000 U.S. cancer deaths per year, including HCC." (PMID 35008356, 2021). "Decreased TTP levels have been demonstrated in malignancies with MYC involvement, and restoring its levels counteracted cancer development." (PMID 34583709, 2021). "MYC plays a critical role in the control of miRNAs expression and, in turn, MYC-regulated miRNAs influence all MYC-driven hallmarks of cancers." (PMID 34503175, 2021). "Among them, MYC is one of the most potent and commonly activated oncogenes, which was mainly amplified or overexpressed in a broad range of human cancers." (PMID 33572152, 2021). "Of 87 patients, 21 patients were analyzed by NGS with 48 selected cancer genes including GNA11, GNAQ and FBXW7, and 66 patients were analyzed for mutations by NGS with 592 cancer genes including BAP1 and SF3B1 mutations as well as MYC amplification." (PMID 34830903, 2021). "While the genetic alterations that bring about c-Myc overexpression in cancer cells are diverse, the most frequent genetic alterations related to MYC are gains in gene copies." (PMID 34503295, 2021).
cancer (continued). "MYC is a group of oncogenes including C-MYC, L-MYC and N-MYC that is generally upregulated and amplificated in cancers." (PMID 34540667, 2021). "A number of HDACi are currently in clinical trials and are yielding exciting results in MYC-driven cancers." (PMID 33801599, 2021). "A molecular hallmark of basal transcriptome has been developed to forecast statin response in breast cancer in vitro and aberrant MYC expression has been proposed as an indicator of statin response in specific cancer types." (PMID 33718197, 2021). "Our results are in line with the current literature reporting that ADSL indirectly modulates Akt phosphorylation and c-MYC activation in other cancer types 6,7." (PMID 33754045, 2021). "The importance of MYC oncoproteins in cancer pathogenesis cannot be overstated as dysregulation of these transcription factors alone is sufficient to promote genome instability and initiate malignant transformation." (PMID 35008802, 2021). "Targeting MYC regulatory pathways, such as MYC ubiquitination and deubiquitination whose deregulation contributes to MYC stabilization in cancer, is another highly desirable approach." (PMID 34178666, 2021). "The importance of BET-mediated regulation of BRCA1 and RAD51 expression in carcinogenesis should be emphasised because their expression was repressed by BETis to a comparable extent as MYC repression in multiple cancer models." (PMID 34681760, 2021). "Our mathematical model quantitatively links the mechanism of oncogene inactivation to cancer response in a transgenic MYC-driven cancer." (PMID 33446671, 2021). "BRD4 amplification was reported to transcriptionally activate c-MYC 9,10, with the consequent promotion of cancer growth, invasion and metastasis 11,12." (PMID 34803511, 2021). "In this mini-review, we will summarize current updates regarding MYC ubiquitination and provide perspectives about these MYC regulators as potential therapeutic targets in cancer." (PMID 34178666, 2021). "On the other hand, MYC has been reported to be responsible for the disruption of the circadian clock in cancer cells, elucidating the possibility of a dysfunctional circadian rhythm in Boran." (PMID 33429951, 2021). "Data published in different studies regarding the functions of c-MYC in different malignant tumors are extremely controversial." (PMID 34204834, 2021). "Cancer cell lines containing MYC amplification were especially sensitive to T-025 treatment, making this a possible biomarker for CLK inhibitor treatment stratification." (PMID 34065983, 2021). "The objective of this work was to evaluate the effect of the drugs isotretinoin and thalidomide on c-MYC expression and cancer-related proteins in an HCC cellular model." (PMID 34641286, 2021). "In conclusion, our findings demonstrate the safety and preliminary clinical activity of single-agent RO6870810 in solid tumours and DLBCL and provide a promising foundation for additional development, potentially in MYC-driven cancers." (PMID 33311588, 2021). "The role of transcriptional regulation has been widely studied in cancer, including discovery of MYC, Sox2, and the FOXO family as important players in cancer initiation and progression." (PMID 34408770, 2021). "As an overexpressed oncogene in various cancers, MYC has a critical role in cancer development, e.g., angiogenesis, apoptosis, proliferation." (PMID 33800752, 2021). "MYC is one of the most studied oncogenes in HGSOC, which has been often associated with BRD4, and whose expression in cancer can be down regulated by BETi." (PMID 34758842, 2021).
cancer (continued). "We screened for genomic alterations associated with this subtyping and found that PSCCE-N subtype was associated with amplification of multiple segments on chromosome 8q, including region harboring cancer gene MYC." (PMID 34145257, 2021). "Current markers of drug responsiveness only enrich for a responding population, and even cancer stratified by MYC will only increase the proportion of patients who respond to a particular therapy." (PMID 34637026, 2021). "FTS has been reported to induce ER stress in MYC-amplified cancer cells as indicated by upregulation of UPR markers." (PMID 33676427, 2021). "c-MYC is constitutively expressed in cancer tissues, which leads in turn, to upregulation of several cancer related genes including, but not limited to, oncogenes." (PMID 34268253, 2021). "The MYC expression pattern is tightly regulated in normal conditions, though MYC is often dysregulated in cancers." (PMID 34372899, 2021). "Aberrant MYC expression in cancer is mainly regulated at transcriptional level by a complex mechanism involving four promoters (P1–P4), different transcription start sites and nuclease hypersensitive elements (NHE)." (PMID 34073075, 2021). "Among the pleiotropic functions of MYC, there is a well-stablished role in promoting proliferation and opposing differentiation both in normal physiological and cancer contexts." (PMID 33659885, 2021). "Accumulated evidence suggests that c-MYC-driven metabolic reprogramming in cancer cells is mainly characterized by increased uptake of precursors, enhanced rate of glycolysis and glutaminolysis, as well as increased synthesis of fatty acids and nucleotides." (PMID 34887764, 2021). "Efforts to develop the MYC G4-targeting DNAi 5T will continue in NHL but are more broadly applicable to other MYC-reliant cancers, such as breast, lung, colon, and many more cancers." (PMID 34577013, 2021). "Accordingly, depletion of Sec62 decreased the expression of Wnt target genes including AXIN2, LGR5 and MYC, all of which play critical roles in maintaining cancer cell stemness and CRC progression." (PMID 33858476, 2021). "Overexpression of FUBP1 alters the expression of the oncogene MYC to promote cancer cell proliferation by interacting with FUBP interacting repressor (FIR) and transcription factor IIH (TFIIH)." (PMID 33987449, 2021). "PVT1 and MYC are co-amplified in a variety of human tumors, and the co-amplification results in MYC stabilization and proliferation of cancer cells." (PMID 33435206, 2021). "MTOR signaling is one of the key oncogenic pathways which is often deregulated in MYC-driven cancers, including NB." (PMID 34565342, 2021). "As an oncogene, MYC can be activated by multiple mechanisms in cancers including transcriptional regulation, mRNA stabilization, and protein overexpression and stabilization." (PMID 34671559, 2021). "The lncRNA EPIC1 has been shown to promote cell cycle progression in cancer cells through interaction with MYC." (PMID 33618674, 2021). "MYC is a well-known Wnt/β-catenin downstream target and exhibits oncogenic roles in various cancers." (PMID 33763420, 2021). "Many genes that are important for cell growth and cancer progression are targeted by c-MYC including those that regulate metabolism." (PMID 33652661, 2021). "MYC has been proved to have a board range of functions, including but not limited to cell biology, cell cycle, apoptosis, the molecular basis of cancer." (PMID 33790943, 2021). "The selection for the co-amplification of TRIB1 and c-MYC, across cancer types, suggests dependency between the two genes." (PMID 34205360, 2021).
cancer (continued). "In these tumors, cancer cells expressing high levels of c-MYC and HDAC2 in the nucleus force relocation of TFEB/TFE3 to the cytoplasm, which inhibits lysosomal biogenesis and autophagy." (PMID 33718382, 2021). "A similar pattern of correlation between FTH1 and c‐MYC or G9a was observed in 921 cell lines representing different types of human cancer." (PMID 34551213, 2021). "For various types of cancer, the role of miRNAs of the let-7 family in regulating the expression of the MYC gene has been described." (PMID 34440124, 2021). "Compound 150 shows exceptionally tight binding to WDR5, strong inhibition of MLL1 histone methyltransferase activity, and excellent activity against MYC-driven cancer cell lines." (PMID 34299488, 2021). "MYC is located on chromosome 8 q24.21 and proven to be a control gene involving cancer through the recruitment of histone acetyltransferase and combining an enhancer box sequence to control about 15% of the human gene expression." (PMID 33540574, 2021). "GCN5 acetylates and reinforces stability of the oncogenic MYC TF that is overexpressed in a majority of human cancers, and in turn MYC facilitates expression of SAGA component genes in a positive feedback loop." (PMID 34112237, 2021). "Taken together, it seems that HADCs are vastly involved in MYC regulation; thus, inhibition of HDACs provoking MYC activity can be greatly beneficial for the treatment of MYC-involved cancers." (PMID 34372899, 2021). "It has previously been reported that MYC and β-catenin have a strong cooperative action in different cancers." (PMID 34446068, 2021). "c-MYC is an oncogene involved in cell growth and differentiation, known to be upregulated in many cancer types." (PMID 34685477, 2021). "Using the reversible c-MYC cancer model, our team found that the dormant cell population contained a significantly higher number of cells that express markers associated with stemness." (PMID 34491463, 2021). "The pharmacological inhibition of IGF-1R signaling led to a substantial eradication of residual disease and a significant delay in cancer recurrence in response to the reactivation of KRAS or c-MYC." (PMID 34491463, 2021). "MYC, one of the four inducible pluripotent stem cell (iPS) factors, is known to be frequently deregulated in human cancers." (PMID 34685497, 2021). "When Wnt signaling is often dysregulated in cancers, possibly due to APC mutation, cytoplasmic β-catenin translocates to the nucleus to activate c-MYC transcription." (PMID 34887764, 2021). "High expression of c-MYC was also linked to reduced apoptosis in CRC, which is a hallmark of cancer development and progression." (PMID 34335790, 2021). "Some cancer types driven by proto-oncogenes, such as MYC and EWS/FLI, are highly dependent on RNA Pol II transcription, and the DDRs to maintain genomic integrity during replication." (PMID 33805800, 2021). "CDK9 inhibition has also been reported as a useful strategy for treating cancers with MYC overexpression." (PMID 34207158, 2021). "The downregulation of FBXW7 leads to the synergistic accumulation of cellular and active chromatin-bound MYC in various types of cancer." (PMID 33494392, 2021).
cancer (continued). "The progressive occupancy of MYC binding sites with progressively reduced affinity in response to increasing levels of MYC has been shown to be important for understanding the normal function of MYC as well as its function in cancer progression." (PMID 34885204, 2021). "HIF-1-induces MAX-interacting protein 1 (MXI-1), which competes with MAX for binding with c-MYC to repress c-MYC activity, in hypoxic cancer cells." (PMID 34359884, 2021). "NSUN2 was found to be a downstream regulator of MYC and promotes cancer cell proliferation by RNAPIII methylation." (PMID 33922187, 2021). "In cancer models, this nutritional stress translates into a reduction in growth through decreased deposition of H3K4me3 on promoters of the cancer-associated genes AKT1, MYC, and MAPK." (PMID 34804127, 2021). "Other recent studies highlight different MYC/microRNA/Autophagy axes that are involved in cancer chemoresistance." (PMID 33430343, 2021). "This function identifies an appropriate therapeutic window where only cancer cells are vulnerable to the downregulation of MYC activity." (PMID 34676047, 2021). "ARID3A is necessary for fetal B lymphopoiesis and B1 cell division, and has also been shown to promote cancers by driving higher MYC expression." (PMID 33679795, 2021). "Suspension of the circadian clock by MYC has been shown to increase the glycolytic phenotype in cancer cell culture." (PMID 34067971, 2021). "In general, under the condition of normoxia, the biosynthesis of mitochondrial respiration and anabolism is facilitated by oncoprotein MYC, allowing cancer cells to proliferate under conditions of adequate oxygen and nutrition." (PMID 34465721, 2021). "BET inhibition by JQ1 downregulates MYC transcription, which is a proto-oncogene overexpressed in cancer cells." (PMID 34716294, 2021). "Next, the frequent but relatively low-amplitude hot zone on the q arm of chromosome 8 is correlated with MYC, which is frequently amplified in numerous cancers." (PMID 34054918, 2021). "CSNK2A1 is involved in cancer progression by regulating various cancer-promoting signaling pathways, such as the MYC, PI3K-Akt, NFκB, and Wnt/β-catenin pathways." (PMID 34359939, 2021). "Some of these oncogenic substrates, such as c-MYC, NOTCH 1, MCL-1, Cyclin E, and c-JUN, likely play a driver role in FBXW7-associated cancers." (PMID 34760892, 2021). "CK2 is primarily seen as an essential regulator of transcription, including that of major cancer transcription activators, such as MYC or β-catenin." (PMID 34208195, 2021). "BET protein inhibitors have been shown to target MYC/MYCN transcription in several cancers, including NB, demonstrating their potential as preclinical anticancer agents." (PMID 34565342, 2021). "In these cancers, a loss of BRG1 causes a reduction of enhancer–promoter interactions, reduced transcription factor occupancy and DNA looping which in turn reduces MYC expression." (PMID 33596994, 2021). "Since deregulated MYC overexpression contributes significantly to human cancers by regulating the expression of genes involved in almost all aspects of the cancer hallmarks, MYC levels and activity must be tightly controlled during normal homeostasis." (PMID 34178666, 2021). "While a relatively limited number of known oncogenes (e.g., RAS, MYC, PIK3CA, EGFR, BCR-ABL) seem to underlie a large percentage of cancers, a variety of new genes have emerged as low-frequency cancer drivers." (PMID 34504101, 2021). "In some types of human and mouse cancers, MYC induces the overexpression of glutamate ammonia ligase (GLUL), also called GS, which is responsible for de novo GLN synthesis." (PMID 34503536, 2021). "Affected genes included FGFR1, IRS1, CLDN4, GRB7, and VCAN, while EZR and MYC were commonly affected in at least four out of five progression stages of the selected cancer levels." (PMID 34069906, 2021).